IL6 (interleukin 6)
Diseases named in the same sentence as IL6 in open-access papers (continued):
Sharing a sentence is not in itself a finding about the gene and the disease.
mastitis (continued). "Compared with those in the untreated mastitis group, the somatic cell counts (SCCs) and the expression of IL-6, IL-1β, and TNF-α in the blood and milk were lower." (PMID 32397071, 2020). "Supplementation of the mixture of LAB and yeast decreased the milk concentration of TNF-α, IL-1β and IL-6 compared with mastitis cows, while single use of yeast or LAB was unable to reduce the concentration of those inflammation cytokine concentration." (PMID 31997024, 2020). "In vivo experiments also proved that treatment with sorafenib significantly reduced the levels of TNF-α and IL-6 in breast tissue from mice mastitis, which was further confirmed by histopathology examination." (PMID 31214565, 2019). "To study the output of cytokines induced by experimental mastitis, we first measured the levels in milk of IL-6 and TNF-α, both of which are well-established inflammatory markers." (PMID 29988549, 2018). "LPS can stimulate mammary epithelial cells to produce the inflammatory cytokines TNF-α, IL-1β, and IL-6, which can interact with and regulate the occurrence and outcome of mastitis." (PMID 29849710, 2018). "In a longer time course udder inoculation model using another subclinical mastitis-causing strain of S. aureus (NCTC13047), IL-6, IL-17A, IL-8, and IL-10 were induced in the alveoli, ducts, gland cistern and teat canal of the bovine mammary gland." (PMID 29705830, 2018). "On the contrary, P4 and B1171 strains induced more severe mastitis with higher bacterial loads, higher neutrophil counts and higher secretion of IL-6 and MIP2, especially for strain P4." (PMID 28727781, 2017). "It was demonstrated that detection of cytokine IL-6 in milk indicated subclinical mastitis earlier than the detection of elevated SCC." (PMID 28101335, 2017). "We analyzed TNF-α, IL-1β, IL-6 and IL-10 levels in mouse mastitis model and the mammary epithelial cells by qRT-PCR and ELISA." (PMID 29340029, 2017). "In a mouse model of mastitis, IL-6 and TNF-α had high local concentrations in E. coli intramammary infections in wild-type mice." (PMID 26976286, 2016). "Previous research has suggested that serum IL-6 can be used as a prognostic biomarker for predicting cows with severe mastitis and prostpartum reproductive diseases like endometritis and retained placenta." (PMID 26479383, 2015). "An association between clinical mastitis and local production of IL1-beta, IL6 and TNF-alpha is suggested in mammary glands of sows." (PMID 25948480, 2015). "Although the genes relevant to milk production are down-regulated in mastitis, lactoferrin and inflammatory cytokines such as interleukin (IL)-1β, IL-6, and tumor necrosis factor-α are up-regulated." (PMID 24308795, 2013). "In vivo, intramammary infusion of TF via the teat canal into the infected quarter of cows with subclinical mastitis downregulated IL-1β/IL-6 mRNA, upregulated TJ genes, and reduced both MLCK expression and the phosphorylation of myosin light chain (MLC), p65, and TAK1." (PMID 41678235, 2026). "A reduction in the IL-1β, IL-6 and IL-8 levels in cows fed Macleaya extract may indicate the resolution of inflammation or successful treatment for mastitis." (PMID 40303387, 2025). "Moreover, Mansour and Zeitoun have demonstrated that high levels of peripheral cytokines such as TNF-α, IL-6, IL-1β, and IFN-γ cause reproductive failure in buffalo cows suffering from either clinical or sub-clinical mastitis." (PMID 39858163, 2025). "Moreover, as one of the most typical messengers in the inflammation family, the expression levels of IL-1β, IL-6, and TNF-α can be used to better evaluate the damage caused by mastitis." (PMID 40438409, 2025). "In addition, IL-6 levels are increased in inflammatory diseases in ruminants, such as mastitis, ruminal acidosis, and metritis." (PMID 40941340, 2025). "IL-6, as an immunomodulatory factor, may mediate the effect of glycemic abnormality on mastitis by activating the inflammatory response." (PMID 40386528, 2025).
mastitis (continued). "It has been proposed that sinomenine hydrochloride may have therapeutic effects on plasma cell mastitis based on its anti–inflammatory and immunomodulatory properties, which are exerted through the downregulation of the IL–6/JAK2/STAT–3 pathway." (PMID 40005889, 2025). "Notably, TNF-α, IL-1β, and IL-6 gene expression in lipopolysaccharide (LPS)-challenged mastitis models peaked at three hours, followed by a gradual decline, reaching the lowest levels at 12 h in liver and udder tissue cells." (PMID 40564979, 2025). "Therefore, this study aimed to determine the relationships of IL-4, IL-6, and IL-10 in mastitis milk with concurrent infections, bacterial pathogens, SCC, and oxidative stress." (PMID 39195804, 2024). "In the presence of mastitis, levels of interleukin (IL)-6, lactoferrin, sIgA, and milk fat globule size were also shown to be higher in comparison to milk from healthy individuals, and the difference in size was larger if accompanied by systemic symptoms like fever." (PMID 39540631, 2024). "In addition, Hagiwara and colleagues also reported lower IL-6 levels in mastitis milk with a single infection." (PMID 39195804, 2024). "This study examines the correlation between interleukin-4 (IL-4), interleukin-6 (IL-6), and interleukin-10 (IL-10) levels in mastitis milk and concurrent infections, bacterial pathogens, somatic cell counts (SCCs), and malondialdehyde (MDA), an oxidative stress marker." (PMID 39195804, 2024). "In fact, IL-6 is a major mediator of acute phase proteins (inflammatory mediators present in the serum), and increased concentrations of this cytokine in milk produced by women with mastitis have been reported previously." (PMID 39896819, 2024). "The results revealed that the binding energy between GYS components and relevant targets was less than -5 kcal/mol, which suggested that TNF and IL-6 might be the primary targets of GYS in mastitis treatment." (PMID 38630770, 2024). "It should be noted that a significant difference in concentration of IL-6 in the milk compared to the control group was recorded for both cows with clinical and subclinical mastitis (487.09 pg/mL vs. 26.6 pg/mL in CM, p < 0.001; and 165.31 pg/mL vs. 26.6 pg/mL, p < 0.001)." (PMID 38612339, 2024). "The higher concentrations of IL-4 and IL-6 in the infected quarters in this study might be due to chronic mastitis in the farms with mastitis control problems." (PMID 39195804, 2024). "Furthermore, studies have shown that certain cytokines, such as interleukin-1 (IL-1), tumor necrosis factor-alpha (TNF-α), and interleukin-6 (IL-6), are significantly elevated in cows with mastitis, reflecting the immune response to udder infection." (PMID 38585704, 2024). "The increasing serum IL-6 in mastitis cows in this study may partially support the ruminal dysbiosis leading to systemic inflammatory effect." (PMID 37662996, 2023). "Similarly, serum levels of TNF-α, IL-1β, and IL-6 were significantly higher in mastitis cows than in the control cows (p < 0.01)." (PMID 37175449, 2023). "Whether the activation of Stat3 in myoepithelium, triggered by Il6 and interferon, in mothers with mastitis, is the etiology of lactation failure via cross-cell signal transduction requires further investigation." (PMID 37833248, 2023). "The milk from animals with mastitis would provide cytokines IL-1, IL-6, and TNF-α." (PMID 37701910, 2023). "Therefore, IL-6 is often used clinically as a monitoring index and as an evaluation standard for mastitis in dairy cows." (PMID 35407209, 2022). "In addition, the detection of IL-6 concentration in milk samples of subclinical mastitis-affected cows predicted inflammation more precisely and earlier than SCC." (PMID 35335696, 2022). "We believe the immunosensor developed in the current study could be a promising tool for the rapid assessment of mastitis by detecting milk IL-6 in dairy cows." (PMID 35407209, 2022).
mastitis (continued). "Contrary, IL-6 was not significantly different between healthy and subclinical mastitis-affected cows questioning its association with other factors." (PMID 35335696, 2022). "Together, data about naturally occurring subclinical and clinical mastitis demonstrate inflammatory responses to intramammary infection driven by IL-1α, IL-4, IL-12, IL-17A, and IFN-γ in subclinical mastitis, and IL-1α, IL-4, IL-6, and IL-17A in clinical mastitis." (PMID 35335696, 2022). "In our study, we found that IL-6 could induce ferroptosis of mammary epithelial cells, and inhibition of IL-6 by USP14 knockdown suppressed ferroptosis, suggesting a novel contribution manner of IL-6 in mastitis." (PMID 35549778, 2022). "Encouragingly, SERS IFA equipped with a portable Raman spectrometer developed in the current study could potentially provide a practical and effective method for early milk IL-6 detection in cow mastitis diagnosis." (PMID 35407209, 2022). "It has also been reported that the concentrations of TNF-α and IL-6 could be downregulated after treatment with a single-dose T4 phage in an E. coli-induced mastitis mouse model." (PMID 35337027, 2022). "Similarly, the analyses revealed that genotypes TT (SNP3) and CC (SNP4) were associated with low IL-6 and high SCC level, which make the dairy cattle more vulnerable to the mastitis development." (PMID 36213405, 2022). "Therefore, detection of IL-6 in milk has been proposed as a predictor marker for subclinical mastitis." (PMID 35163731, 2022). "Therefore, the rapid and high-sensitivity detection of IL-6 is of great significance in the early prevention and diagnosis of inflammatory diseases such as mastitis in dairy cows." (PMID 35407209, 2022). "Additionally, the upshot of a study infers that not only SCS and SCC but IL-6 and IFN-γ association can be establish with genetic markers while selecting genetically mastitis resistance dairy cattle." (PMID 36213405, 2022). "In the current study, the extraordinarily high amount of IL-6 in sera samples of mice infected with biofilm forming NT S. aureus suggests an important role of IL-6 in virulence of strong biofilm forming S. aureus in mouse mastitis model." (PMID 34827779, 2021). "Nevertheless, we investigated the presence of IL-6 and IL-1ß by ELISA in one “mastitis” quarter." (PMID 34798884, 2021). "IL-6 in quarter milk has been proven as a prediction marker of bovine mastitis." (PMID 34827779, 2021). "In addition, fever and systemic inflammation also correlate with IL-6, for example IL-6 was higher when mastitis occurred in the lobes." (PMID 31174304, 2019). "The mechanism of Paeoniae Radix Alba, Glycyrrhizae Radix et Rhizoma, Bupleuri Radix, Semen Vaccariae, herba houttuyniae, and pericarpium trichosanthis kirilowii et multilobae in treating mastitis might be that they can decrease IL-6 level." (PMID 30911319, 2019). "vB_EcoM-UFV13 used in an animal model for mastitis reduced the total bacterial load by 90%, as well as inducing pro-inflammatory cytokines such as IL-6 and TNF-α, which makes it a potential biological agent capable of controlling acute infections caused by E. coli dairy cows." (PMID 29717158, 2018). "The author concluded that the detection of IL-6 in milk could be a reliable prediction marker for subclinical mastitis." (PMID 28101335, 2017). "We detected significantly elevated levels of TNF-α and IL6 protein secreted in medium by INFs compared with that secreted by NFs, suggesting that mammary stromal fibroblasts contribute to the inflammatory response during mastitis." (PMID 27272504, 2016). "IL-6 is a powerful, pro-inflammatory cytokine with wide impact on the host response against various pathogens, and it has been shown previously that IL-6 is elevated during mastitis." (PMID 27713743, 2016).
mastitis (continued). "Furthermore, given that tumor necrosis factor-α (TNF-α) and interleukin (IL)-6 are well-known inflammatory mediators during mastitis, their secretion in medium by INFs and NFs were examined using ELISA kits." (PMID 27272504, 2016). "However, when mice developed mastitis caused by Coagulase-negative staphylococci (CNS; Staphylococcus aureus, S. chromogenes, S. fleurettii), the inoculated S. aureus produced IL-6 and IL-1β but not TNF-α." (PMID 41148692, 2025). "High levels of SCC are not only directly related to an increased risk of subclinical mastitis but may also suppress the expression of lactation-related genes and proteins, such as STAT5 and LALBA, through inflammatory factors like IL-6 and TNF-α, leading to decreased milk yield." (PMID 40941289, 2025). "In future studies, the inflammatory factors (TNFα, IL-2, IL-6), the number of S aureus in mammary gland, and the underlying mechanisms need to be detected, which may provide a theoretical basis for CTE application in the treatment of S. aureus mastitis." (PMID 41309393, 2025). "Alterations in the expression of key cytokines (e.g., IL-6) and antimicrobial peptides (e.g., CATH) in milk somatic cells indicate that the mammary defense system is compromised in hypocalcemic cows, increasing their susceptibility to mastitis and other periparturient infections." (PMID 40284849, 2025). "Additionally, the expression levels of pro‐inflammatory cytokines IL‐6, TNFα, and IL‐1β were markedly increased (P < 0.01), confirming the successful establishment of the mastitis model." (PMID 40552401, 2025). "Increased concentrations of IL-6 in milk and blood were detected by the authors in cows and in ewes with natural infection of the udder but also in the case of experimentally induced mastitis and even after administration of bacterial lipopolysaccharides (LPS)." (PMID 38612339, 2024). "IL-6 levels in milk from HE cows ranged from 6.09–80.24 pg/mL (median 26.6 pg/mL) and were significantly lower than in milk from both cows with clinical and subclinical mastitis (487.09 pg/mL vs. 26.6 pg/mL in CM, p < 0.001; and 165.31 pg/mL vs. 26.6 pg/mL in SCM, p < 0.001)." (PMID 38612339, 2024). "IL-6 is also an important cytokine that could detect early stages of subclinical mastitis." (PMID 39195804, 2024). "Luteolin inhibited the expression of TNF-α, IL-1β, and IL-6; suppressed IκBα and NF-κB p65 phosphorylation levels; and downregulated the expression of MMP-2 and MMP-9 in S. aureus-induced mastitis, showing its potential in reducing tissue damage and inflammation caused by S. aureus-induced mastitis." (PMID 36111166, 2022). "Additionally, abnormal expression of IL6 was revealed to be due to altered DNA methylation rather than genetic mutation during clinical mastitis." (PMID 33193625, 2020). "In addition, cows with subclinical mastitis caused by CNS produce a local immune response in the mammary gland, similar to a variety of inflammatory immune factors including TNF-α and IL-6 produced by Th1 and Th2-mediated immune responses in the presence of exogenous infection." (PMID 31860659, 2019). "It has been reported that breast milk from women with subclinical mastitis exhibits a predominant Th1/proinflammatory cytokine profile, including TNF-α, IL-6, IL-8, IL-17, RANTES, IL-12p40/70, IFN-α, IFN-γ, CXCL-9, IP-10, MIP-1α, and MIP-1β." (PMID 40564173, 2025). "Interleukin-6 (IL6), a multifunctional cytokine with established roles in mastitis, was another high-confidence target." (PMID 41452937, 2025). "Mouse mastitis induced in this study by S. aureus was characterized by a broad increase in proinflammatory cytokines, particularly for IFN-γ, IL-1β, IL-6, and GM-CSF to stimulate and recruit macrophages and neutrophils as is expected for S. aureus IMIs." (PMID 40757863, 2025). "IL-6 induces the production of acute phase proteins (APP) from the liver, and APP has been identified in milk or serum in mastitis or metritis." (PMID 40941340, 2025).
mastitis (continued). "In conditions such as mastitis, the release of pro-inflammatory cytokines, including TNF-α, IL-1β, IL-6, and IL-8, significantly intensifies the inflammatory response, thereby exacerbating tissue damage and pathological alterations." (PMID 40666730, 2025). "During mastitis, mammary tissues exhibit elevated levels of inflammatory factors such as TNF-α, IL-6, IL-8, and IL-1β." (PMID 39860009, 2025). "Utilizing the PPI network, the topological parameters of Betweenness unDir, Closeness unDir, and Degree unDir were employed to predict the core targets for mint in treating mastitis in dairy cows, which include TNF, IL–6, STAT–3, IL–1β, FGF–2, IFNG, and ESR–1." (PMID 40005889, 2025). "Our molecular docking analysis revealed that TNF and IL-6 were primary targets for interaction with the active GYS constituents, quercetin, and luteolin, against mastitis." (PMID 38630770, 2024). "Mean concentrations of IL-1ra and IL-6 in milk produced by healthy controls and SCM cases remained unchanged from the week prior to the week of mastitis detection." (PMID 39896819, 2024). "When PUE was added to the dairy diet of the healthy cows and cows with mastitis, the levels of TNF-α, IL-1β, and IL-6 in the whey of the cows on day 7 were significantly lower than those on day 0 (p < 0.01)." (PMID 37175449, 2023). "After identifying the bacterial biomarkers in both groups, we illustrated the correlation of mastitis parameters (SCC, NAGase, IL-6) with the bacterial biomarkers at the species level." (PMID 37662996, 2023). "The levels of IL-1β, IL-6, TNF-α, COX-2, and iNOS in the serum of cows with clinical mastitis were significantly higher than those in the healthy cows (p < 0.001)." (PMID 36875515, 2023). "The pro-inflammatory cytokines IL-12, IL-6, TNF-α, and IL-1β were found to be significantly elevated in lactating cows suffering from clinical mastitis." (PMID 36899749, 2023). "In mastitis, immune cell activity is mainly regulated by the pro-inflammatory cytokines TNF-α, IL-1β and IL-6, which are typically pro-inflammatory cytokines." (PMID 36090098, 2022). "This value was also much lower than the threshold of the clinical mastitis of dairy cows, demonstrating the ultra-high sensitivity of the proposed SERS IFA for IL-6 detection." (PMID 35407209, 2022). "Up to the knowledge, Klebsiella pneumoniae promotes the production of the inflammatory cytokine genes IL-6, IL-8, IL-1β, and TNF-α in mastitis already after 6 h." (PMID 35335696, 2022). "For example, treatment with Morin in LPS-induced mastitis and LPS-induced acute lung injury significant decreased the expression of inflammatory cytokines, including TNF-α, IL-1β, and IL-6." (PMID 35705830, 2022). "Propionate decreased the inflammatory factors (IL-1β, IL-6, and TNF-α) via inhibiting NF-κB and HDAC in in-vitro and in-vivo mastitis models." (PMID 36145063, 2022). "Our study showed that the mastitis immunological profile in the mammary gland may be related to specific HMOs, as the levels of the branched hexasaccharide LNH, its disialylated derivative DSLNH, 3’SL, and DFLac were positively associated to some pro-inflammatory cytokines (IL2, IL6, IL17 and IFNγ)." (PMID 35079053, 2022). "Both experimentally induced or naturally occurring mastitis results in an increase in the somatic cell count (SCC) and levels of produced cytokines (interleukin (IL) IL-1, IL-2, IL-4, IL-5, IL-6, IL-8, IL-10, and IL-12) in milk." (PMID 35335696, 2022). "The mRNA results showed that the contents of inflammatory mediators IL-1β, IL-6, and TNF-α in mastitis tissues were significantly higher than those in the control group (p < 0.01)." (PMID 36355118, 2022). "MECs can synthesize and secrete inflammatory chemokines and pro-inflammatory cytokines such as interleukin-1 beta (IL-1β), interleukin-6 (IL-6), interleukin-8 (IL-8), and tumor necrosis factor (TNF-α), which are crucial for the occurrence of mastitis." (PMID 35681915, 2022).